CTLA4 (cytotoxic T-lymphocyte associated protein 4)
Diseases named in the same sentence as CTLA4 in open-access papers (continued):
Sharing a sentence is not in itself a finding about the gene and the disease.
lymphoma (continued). "In veterinary medicine, although previous studies revealed high expression of CTLA-4 in dogs with oligodendroglioma and histiocytic sarcoma, the expression of this marker in lymphoma had not previously been reported." (PMID 30040869, 2018). "We found that PD-1/CTLA-4 ab-treated lymphomas that contained many infiltrating T cells also had multiple HEVs, whereas lymphomas that had few or no infiltrating T cells did not contain these structures." (PMID 27186886, 2016). "However, data from a cord blood-humanized mouse model suggest that both PD-1 and CTLA-4 are expressed on T cells and that PD-1/CTLA-4 blockade increases T cell infiltration of tumors, promotes T cell activation, and eventually leads to a drastic reduction of the size of EBV-induced lymphomas." (PMID 40361408, 2025). "Combinatory treatment with CpG-Stat3 siRNA and CTLA4 antibody in A20 lymphoma tumor-bearing mice significantly increased the percentages of IFNγ and/or granzyme B (GZMB) producing CD4+ T cells and CD8+ T cells in tumors compared to either CpG-Stat3 siRNA or CTLA4 antibody alone." (PMID 39618825, 2024). "Furthermore, EVs trigger the overexpression of CTLA-4 on CD8 + T-cells, which indicates that EV blockade could serve as a potential therapeutic strategy for lymphoma patients." (PMID 37884996, 2023). "Similarly, lymphoma cells lacked CTLA4 expression, which was mostly present in regulatory T cells of cluster TC-1." (PMID 34583709, 2021). "So far, CTLA4 inhibition is not commonly used in lymphoma therapy." (PMID 29564225, 2018). "Besides inducing T-cell anergy and, thus, fostering immune escape, CTLA4 has also a direct oncogenic effect: a fusion of the two opponents CTLA4 and CD28 has recently been described in a variety of T-cell lymphomas and proposed to be a major driver of lymphoma development." (PMID 29564225, 2018). "For lymphoma patients, different interesting target could be considered for iPET, such as general T cell markers (CD3, CD4, and CD8), immune-checkpoints (PD-1, PD-L1 or CTLA-4) or biomarkers of the immune response (interferon-gamma, interleukin-2, and granzyme B)." (PMID 33803667, 2021). "Similarly, activation of CD152/ CTLA4 induces cell proliferation and tumor growth in lymphomas through activation of the TYK2-STAT3 pathway, and anti-CD152 mAb ipilimumab could be a potential targeted therapeutic for lymphomas." (PMID 34696358, 2021). "In a lymphoma mouse model, a TLR9 agonist (intratumoral CpG) in combination with anti-OX40 and anti-CTLA-4 cured large and systemic lymphoma tumors without the need for chemotherapy." (PMID 30853982, 2019). "Although PD-1/CTLA-4 blockade greatly decreased the growth rate of EBV-induced lymphomas in the cord blood humanized mouse model, and extended the survival of EBV-infected mice, this therapy alone did not ultimately prevent death due to EBV+ lymphoma." (PMID 27186886, 2016).
diabetes (88 papers, 2002 to 2026). "In humans, CTLA-4 deficiency leads to a clinical phenotype consisting of autoimmune pancytopenia, encephalomyelitis, thyroiditis and diabetes mellitus." (PMID 41010821, 2025). "In a large case study, over 76% of cases of PD-1 inhibitor-associated diabetes mellitus occurred in combination with a CTLA-4 medication." (PMID 39130825, 2024). "Polymorphisms on CTLA4 gene have been implicated in diabetes and thyroid disease, rheumatoid arthritis, primary biliary cholangitis, and spontaneous abortion." (PMID 37342323, 2023). "Recently, some pilot studies also analyzed potential associations between CTLA-4 gene polymorphisms and the much more prevalent type 2 diabetes mellitus (T2DM)." (PMID 30988065, 2019). "In fact, we see that treatment with IC87114 abrogates the protective effects of CTLA4-Ig treatment and causes a quicker progression to diabetes after cell transfer." (PMID 26783747, 2016). "In dogs, certain CTLA4 promoter polymorphisms and haplotypes have been associated with both increased and decreased susceptibility to diabetes in multiple breeds, and to hypoadrenocorticism in Cocker spaniels and Springer spaniels." (PMID 26401336, 2015). "In contrast, in a different TCR-transgenic diabetes model, CTLA-4 deficiency abrogated the ability of Treg to control disease." (PMID 23849743, 2013). "The Ctla4 gene is a diabetes candidate gene for T1D and its association is well documented in the literature." (PMID 22615750, 2012). "Caspase inhibitor therapy (EP1013) in combination with costimulation blockade (CTLA4-Ig) too prevented engraftment phase islet loss and markedly reduced islet mass required to reverse diabetes." (PMID 22046502, 2011). "However, CTLA-4–deficient Treg lack suppressor function and were unable to regulate disease in an adoptive transfer model of diabetes." (PMID 38226924, 2024). "Similarly, in an autoimmune model for diabetes, adoptively transferred CTLA-4-deficient Treg were unable to prevent the destruction of the pancreas and the induction of diabetes." (PMID 37342323, 2023). "In addition, an international registry identified combination therapy, diabetes, obesity, and anti-CTLA-4 therapy were independent risk factors for cardiotoxicity." (PMID 36035942, 2022). "Nevertheless, based on the known data we may hypothesize that known CV comorbidity with diabetes may be a combined risk factor in patient treated with anti-CTLA4+anti-PD-1 immunotherapy." (PMID 35096992, 2021). "Similar to CTLA-4 blockade, knockout or blockade of PD-1 or polymorphisms in PD-1/PD-L1 genes in mice leads to autoimmune-like conditions such as cardiomyopathy, progressive arthritis, lupus-like glomerulonephritis, diabetes, Graves’ disease, and multiple sclerosis." (PMID 39247203, 2024). "Mutations in the antigen 4 gene in CTLA-4, which is an important negative regulator of the activation of T cells, are involved in type 1 diabetes mellitus (DM) and autoimmune thyroid diseases (Graves’ disease and Hashimoto’s thyroiditis)." (PMID 34944008, 2021). "Approximately 97% of all reported cases of ICI-induced diabetes occurred in patients treated with PD-1/PD-L1 inhibitor or a combination of PD-1/PD-L1 inhibitor plus CTLA-4 inhibitor, whereas reports of cases on CTLA-4 inhibitor monotherapy are very rare." (PMID 40662006, 2025). "Complementary evidence from chronic inflammatory and cardiovascular disease models shows progressive suppression of PD-1/PD-L1 and CTLA-4 signaling, supporting the concept that diabetes represents a systemic immune-checkpoint–impaired state." (PMID 41463504, 2025). "We profiled the expression of PDCD1 (PD-1) and CTLA4, two immune checkpoint genes previously implicated as defining immunogenic subsets of PDAC-associated diabetes." (PMID 40244011, 2025). "Murine models reveal that IL-33 drives the expansion of highly suppressive GATA3+CTLA4+ Tregs that, in turn, prevent the onset of diabetes." (PMID 39704171, 2024).
diabetes (continued). "It has been demonstrated that in approx. 60% of LADA patients, polymorphisms of the CTLA-4 gene, in particular the G CTLA-4 alleles, is observed, and the likelihood of the disease increases if diabetes is present in the family." (PMID 34836227, 2021). "Here, we examine post-onset diabetes progression in local patients from the Children’s Hospital of Wisconsin and participants in the TrialNet CTLA4-Ig (Abatacept) trial (TN-09)." (PMID 30167736, 2018). "Plasma of untreated individuals with diabetes was therefore supplemented with 0 μg/ml, 25 μg/ml (estimated steady-state trough level) or 82 μg/ml CTLA4-Ig (estimated steady-state high level)." (PMID 30167736, 2018). "Others have shown that the survival of donor-derived (porcine) CTLA4-IgG4 gene-modified porcine islet xenografts was significantly prolonged in rats with diabetes." (PMID 23922766, 2013). "CTLA4 protein expression was reported lower in the patients with diabetes and with autoimmune thyroiditis as compared in controls." (PMID 23112798, 2012). "Treatment with anti-CTLA-4 mAb of BDC2.5/NOD mice provoked a rapid onset of diabetes, indicating that a higher CTLA-4 presence was required for suppression of autoimmune phenomenon in these mice." (PMID 16259622, 2005). "As a negative regulator of T cell activation, blockade of CTLA-4 by monoclonal anti-CTLA-4 antibody provokes a rapid onset of diabetes in BDC2.5/NOD mouse model." (PMID 16259622, 2005). "Impaired fatty acid oxidation (FAO), a critical pathway for memory T cell differentiation and sustained CTLA-4 expression, becomes markedly compromised in diabetes due to disrupted lipid metabolism and mitochondrial dysfunction, thereby diminishing T cell longevity and checkpoint upregulation." (PMID 41463504, 2025). "Published case reports of anti-CTLA-4 CIADM do not provide clear evidence of insulin deficiency or thorough exclusion of other forms of diabetes." (PMID 37997380, 2024). "The reported incidence of ICI-induced diabetes varies between 0.9 and 2%, with a significant proportion of cases, up to 76%, attributed to the use of anti-PD-1 agents, 8% to anti-PD-L1 agents, and only 4% to the use of anti-CTLA-4 agents." (PMID 37779728, 2023). "In addition to the current treatment for diabetes with CTLA4-Ig, utilizing CTLA4 to prevent the onslaught of autoimmune cells to the islets is a suitable place to start." (PMID 36405706, 2022). "We identified changes in both β cells and immune cells following CPI and differential effects of anti–CTLA-4 and anti–PD-L1 mAbs that may account for the clinical differences in diabetes with these CPIs." (PMID 35925682, 2022). "Although diabetes only occurred following anti–PD-L1 treatment, both anti–PD-L1–treated NOD mice and anti–CTLA-4–treated NOD mice developed immune infiltrates, indicating that differences in the immune and/or β cells account for the susceptibility to diabetes." (PMID 35925682, 2022). "Therefore, it is useful to design PD-L1 and CTLA4 gene-based strategies for the treatment of diabetes." (PMID 36405706, 2022). "Immunotherapies such as PD/PD-L and CTLA-4 inhibitors can reduce the production of insulin from islet cells as in type 1 diabetes mellitus, whereas targeted treatments such as PI3K/mTOR inhibitors can induce insulin resistance similar to that seen in type 2 diabetes mellitus." (PMID 34830886, 2021). "Studies have reported that HLA-DR3, CTLA4, and PTPN22 may be common genetic susceptibility genes for diabetes and hypothyroidism." (PMID 34258276, 2021). "Significant allele and haplotype associations have been reported between the CTLA4 promoter region and diabetes, although not for immune-mediated haemolytic anaemia." (PMID 32835228, 2020). "Recently, a clinically relevant immunoregulatory strategy based on treatment of NOD mice with murine Thymoglobulin (mATG) and CTLA4-Ig to prevent allo- and autoimmune activation in a stringent model of islet transplantation and diabetes reversal was investigated." (PMID 22046502, 2011).
diabetes (continued). "The newly identified Cia40 locus includes the Ctla4 (CD152) gene, which is a strong candidate associated with spontaneous diabetes identified in crosses between C57Bl and nonobese diabetic strains." (PMID 16507151, 2006). "However, in the presence of blocking anti-CTLA-4-mAb, immunized adoptive transfer recipients rapidly developed diabetes." (PMID 12885158, 2002). "The reported diabetes incidences were 0.8 and 2.3% following ICI treatment with either anti-PD-1 or anti-CTLA-4 monotherapy." (PMID 36149449, 2022). "Four potential TCF/LEF sites have been identified within the 800 bp upstream of the start codon in human CTLA4, one of which contains the C(− 318) T SNP associated with altered promoter activity and with susceptibility to Grave’s disease, autoimmune pancreatitis but not diabetes." (PMID 32835228, 2020). "We subsequently performed a systematic review and present an overview of similar cases of diabetes mellitus related to CTLA-4, PD-1, PD-L1 or a combination of CTLA-4 and PD-1 checkpoint inhibitors." (PMID 31330498, 2019). "Intracellular CTLA-4 was closely related to the suppressor function of regulatory T cells and reported the close relationship with autoimmune disease, including Graves’ disease, type 1 diabetes mellitus (DM)." (PMID 27818660, 2016). "Using CTLA-4−/− TCR-transgenic Tregs that, we had shown, lack the capacity to regulate diabetes 116, we demonstrated that ligand trans-endocytosis in vivo was strictly dependent on CTLA-4 expression." (PMID 24712457, 2014). "The mRNA expression level for CTLA4, as well as ICOS and GITR, was found lower in regulatory T (Treg) cells of children with newly diagnosed diabetes as compared to the healthy controls." (PMID 23112798, 2012). "We have demonstrated that transgenic expression of PD-L1 (ligand of PD-1) or a membrane-bound, agonistic single-chain anti-CTLA-4 Fv antibody (anti-CTLA-4 scFv) on islets in NOD mice reduces the severity of insulitis and suppresses the development of diabetes." (PMID 22690214, 2012). "Of note, diabetes has been described in the case of patients treated with anti-PD-1/PD-L1, but not with anti-CTLA-4." (PMID 30400055, 2019). "Of note, given the increase of use of anti-CTLA-4/anti-PD-1 association, we report here recommendations that can be applied whatever the ICPI used except for special cases (such as diabetes that has never been reported with anti-CTLA-4)." (PMID 30400055, 2019). "In this same study, no mice developed diabetes in response to administration of anti-CTLA-4 antibodies." (PMID 30400055, 2019). "Contrary to previous reports, no distinct immunogenic signature was identified in PDAC with diabetes, as key immune checkpoint genes (Programmed Cell Death Protein 1 (PDCD1), Cytotoxic T-Lymphocyte Associated Protein 4 (CTLA4), Programmed Death-Ligand 1(PD-L1)) were not differentially expressed." (PMID 40244011, 2025). "Additionally, preclinical studies support our results, suggesting that it is a PD-1 inhibitor rather than a CTLA-4 inhibitor that rapidly induced diabetes in adult mice." (PMID 35431928, 2022). "In the NOD mouse model, anti–PD-L1 but not anti–CTLA-4 induced diabetes rapidly." (PMID 35925682, 2022). "However, combination treatment with twice daily oral administration of IC87114 and intraperitoneal injections with CTLA4-Ig every other day for 10 days did not lead to protection from diabetes either after transfer of naïve cells or pre-activated Th1 cells." (PMID 26783747, 2016). "Similarly in Idd3/5.2 and Idd3/5.3 strains where the congenic Idd5.1 locus containing the CTLA4 gene is absent, IL-2 alone cannot prevent diabetes induced by PDL1 blockade." (PMID 24586872, 2014). "This 78-year-old woman without prior history of diabetes developed CPI-DM approximately 17 days after receiving 1 dose of durvalumab (anti–PD-L1) and tremelimumab (anti–CTLA-4) for myelodysplastic syndrome." (PMID 35925682, 2022).
diabetes (continued). "However, blockade of this pathway was noted to only induce diabetes in neonates and not in adult mice, suggesting that the role of CTLA-4 may be limited to inhibiting the activation of naïve T cells." (PMID 28031819, 2016). "Preclinical studies reveal PD-1 inhibition accelerates diabetes onset across age groups, while CTLA-4 inhibition primarily affects young non-obese diabetic mice, indicating distinct roles: CTLA-4 regulates naïve T cells, whereas PD-1 controls both naïve and autoimmune T cell activation." (PMID 40388765, 2025). "Diabetes was precipitated by anti–PD-L1 but not anti–CTLA-4 mAb treatment in 7-week-old NOD mice, consistent with our clinical experience of the selectivity of CPI-DM following PD-1 pathway blockade and previous studies on PD-1 blockade in the model." (PMID 35925682, 2022).
Hepatitis (83 papers, 2014 to 2026). Inflammation of the liver. "The reported incidence of immunotherapy-associated hepatitis in the literature varies according to the different agents: 2–15% in CTLA-4 inhibitors, 0–3% in PD-1 inhibitors, and 0–6% in PD-L1 inhibitors." (PMID 38611049, 2024). "The overall incidence of hepatitis induced by immunotherapies has been reportedly low ~2–15%, and CTLA4 inhibitors have been reported to be associated with more cases of immune-mediated hepatitis (IH) than PD1/PDL1 inhibitors." (PMID 38259857, 2023). "The hepatocellular pattern was significantly associated with hepatitis severity and anti-CTLA-4 inhibitor-containing regimen." (PMID 37138674, 2023). "Hepatitis is one of the most common IRAE-associated diseases with the uses of anti-CTLA-4, anti-PD-1, and their ligands." (PMID 37631034, 2023). "Previously, another group reported that granulomatous hepatitis was observed in liver with grade ≥ 3 hepatitis caused by anti-PD-1/PD-L1 or CTLA-4 immunotherapies." (PMID 35256688, 2022). "Hepatitis is one of the most common irAE causing severe (CTCAE 3–4) toxicity in anti-PD-1 & anti-CTLA4 therapy with incidence rates reported up to 33%." (PMID 36503532, 2022). "Together, these data support age as a validated risk factor for the development of hepatitis in the first 100 days after anti-PD-1 & anti-CTLA4 therapy." (PMID 36503532, 2022). "Rechallenge with the combination of anti–PD-1 and anti–CTLA-4 antibodies after hepatitis or another irAE carries a high risk of recurrent toxicity." (PMID 35126126, 2021). "Checkpoint inhibitor-induced hepatitis is an immune-related adverse event of programmed cell death protein 1 (PD-1) inhibition, cytotoxic T-lymphocyte associated 4 (CTLA-4) inhibition or the combination of both." (PMID 33634373, 2021). "CTLA4-Ig monotherapy proved remarkably effective in treating subject 1 enterocolitis, hepatitis, and pericarditis, although its use was associated with progressive antibody deficiency." (PMID 30087679, 2018). "CTLA-4 primarily affects T cell priming by antigen-presenting cells in lymphatic organs, whereas PD-1/PD-L1 affects T cell exhaustion on the periphery, and the difference in action sites causes the difference in the incidence and severity of hepatitis." (PMID 38291394, 2024). "Treatment with ipilimumab after PD-1 inhibition could then result in combined inhibition of PD-1 and CTLA-4 and increase the risk of hepatitis." (PMID 33634373, 2021). "Therefore, the use of CTLA-4 requires caution, especially in those already at risk of hepatitis." (PMID 38291394, 2024). "Immune-related AEs (IRAE) during concurrent therapy occurred in seven of 10 patients receiving anti-CTLA-4/PD-1 combination, including hepatitis (n = 5; grade 2 in 1, grade 3 in 4)." (PMID 40665019, 2025). "Incidence of ICI-induced hepatitis was reported to be 0.7% to 2.1% in PD-1, and much higher in CTLA-4 population (up to 12-16%), notably, fulminant hepatic failure was relatively rare (0.1%‐0.2%)." (PMID 41346594, 2025). "They found that hepatitis was more common in patients treated with CTLA-4 inhibitors, whereas all cases of cholangitis occurred in those treated with PD-1 inhibitors." (PMID 40423705, 2025). "In contrast, adding a CTLA-4 inhibitor to a PD-1 inhibitor resulted in a markedly higher incidence and severity of hepatitis: elevated AST levels in 16.7% of patients (grade ≥ 3 in 5.9%) and elevated ALT levels in 18.2% (grade ≥ 3 in 8.4%)." (PMID 38291394, 2024). "A recent study showed a significantly earlier onset of hepatitis in patients treated with anti-CTLA-4 antibodies compared to those receiving anti-PD-1/PD-L1 antibodies." (PMID 39064558, 2024). "There is a higher rate of immune-related adverse events, including hepatitis, in patients undergoing combination therapy with CTLA-4 and PD-1 inhibitors, indicating a cumulative effect." (PMID 39280244, 2024).